MMP2 (matrix metallopeptidase 2)
Diseases named in the same sentence as MMP2 in open-access papers (continued):
Sharing a sentence is not in itself a finding about the gene and the disease.
spinal muscular atrophy (1 paper, 2025). A motor neuron disease that affect the muscles, and characterized by muscle weakness and atrophy resulting from progressive degeneration and irreversible loss of the anterior horn cells in the spinal cord (i.e., lower motor neurons) and the brain stem nuclei. "Schoser and colleagues, using immunohistochemistry on muscle biopsies from a small cohort (n = 5) of patients with ALS, spinal muscular atrophy, and chronic axonal neuropathies, observed strong MMP-9 immunoreactivity—and to a lesser extent, MMP-2 and MMP-7—in all samples." (PMID 41009467, 2025).
spinal stenosis (1 paper, 2009). Narrowing of the spinal canal. "In addition, we found that the expression of MMP-2 was statistically higher in the patients with spinal stenosis than it was in those patients with disc herniation (p < 0.05)." (PMID 19885059, 2009). "Considering the well-known ability of MMP-2 to degrade elastin, its high expression in the ligamentum flavum of spinal stenosis patients suggests that it may be, at least partially, responsible for the severe loss and disorganization of the elastin fibers observed in that pathological condition." (PMID 19885059, 2009). "Western blot analysis demonstrated the expressions of active MMP-2, MMP-3, and MMP-13 in the ligamentum flavum specimens of the spinal stenosis patients and the disc herniation patients." (PMID 19885059, 2009). "The expressions of active MMP-2 and MMP-13 were significantly higher in the spinal stenosis samples than that in the disc herniation samples (both p < 0.05)." (PMID 19885059, 2009). "Immunohistochemical analysis demonstrated that MMP-2, MMP-3, and MMP-13 were positively stained on the ligamentum flavum fibroblasts of the patients with spinal stenosis and disc herniation, respectively." (PMID 19885059, 2009). "The mean density (arbitrary units) of active MMP-2 and MMP-13 was statistically higher in the spinal stenosis specimens than that in the disc herniation specimens (324.75 ± 63.66 vs. 238.00 ± 76.05, respectively, p < 0.05; 340.00 ± 48.63 vs. 248.50 ± 52.09, respectively, p < 0.05)." (PMID 19885059, 2009). "While we found increases of MMP-2 and MMP-13 in the spinal stenosis samples, this does not necessarily mean that these factors are either solely or even partially responsible for the histologic changes associated with the clinical condition." (PMID 19885059, 2009).
status epilepticus (1 paper, 2022). Status epilepticus is defined as a continuous seizure lasting more than 30 min, or two or more seizures without full recovery of consciousness between any of them. "In a rat model of epileptogenesis induced by electrical stimulation, expression of MMP-2 was increased in CA3 and entorhinal cortex at seven days after status epilepticus." (PMID 36499038, 2022).
Strabismus (1 paper, 2017). A misalignment of the eyes so that the visual axes deviate from bifoveal fixation. "Some of the trends in gene expression differences between horizontal muscles from patients with strabismus, notably for MMP2 and TIMP2, were similar to those reported previously." (PMID 29302405, 2017).
stress-related disorder (1 paper, 2025). Stress-related disorders are mental health disorders that are a result of an atypical response to both short and long-term anxiety due to physical, mental, or emotional stress. "Thus, over the last 20 years, research has focused on the role of MMP-2,9 in various psychiatric disorders, including drug and stress-related disorders." (PMID 40894006, 2025).
synucleinopathies (1 paper, 2022). "In contrast, MMP-2 is reduced in synucleinopathies, suggesting its causal role in these diseases." (PMID 35573838, 2022).
tendonitis (1 paper, 2023). "Changes in the MMP family during tendon healing were another important factor in the formation of adhesive texture, studies have shown that when tendonitis occurs, the activity of MMP2 and MMP9 would change." (PMID 36859314, 2023).
testicular tumors (1 paper, 2021). "PTTG1 and its target MMP-2 were analyzed in human testicular tumors using the Atlas database." (PMID 33430117, 2021).
Thrombocytopenia (1 paper, 2021). A reduction in the number of circulating thrombocytes. "Then, in addition to the thrombocytopenia induced by bloodstream TS sialidase activity, it is also involved in the modulation of MMP-2." (PMID 33891967, 2021).
thymic epithelial tumors (1 paper, 2023). "The gelatinolytic activity of MMP-2 increases with invasiveness in thymic epithelial tumors, and the expression of MMP-2 is indicative of a poor outcome." (PMID 38201593, 2023).
trichorhinophalangeal syndrome type I (1 paper, 2024). An autosomal dominant malformation syndrome caused by mutations in TRPS1 characterized by distinctive craniofacial and skeletal abnormalities. "Previous studies show that miR-222-3p has an oncogenic effect by regulating MMP2 (matrix metalloproteinaza), MMP9, TRPS1 (trichorhinophalangeal syndrome type 1), and CDKN1C/p57 (cyclin-dependent kinase inhibitor 1C)." (PMID 38542261, 2024).
tympanosclerosis (1 paper, 2025). The formation of dense connective tissue in the tympanic membrane that does not necessarily cause or lead to loss of hearing. "MMP-2 and 9, which have been studied in animal models of tympanosclerosis, were investigated in our study in the sclerotic tissues of patients with tympanosclerosis and their relationship with hearing outcomes was evaluated." (PMID 40468054, 2025). "In a study conducted with human serum samples, serum levels of MMP-2 and 9 were found to be significantly higher in patients with tympanosclerosis." (PMID 40468054, 2025). "In addition, our study constitutes a unique example in the literature in terms of investigating the relationship between MMP-2 and 9 and hearing test results in tympanosclerosis." (PMID 40468054, 2025). "Compared with the inadequacy of animal models of tympanosclerosis to mimic the chronic process, our study reveals the late results of MMP-2 and MMP-9 in patients with tympanosclerosis." (PMID 40468054, 2025). "In our study, the increased MMP-2 and decreased MMP-9 staining rates in tympanosclerosis suggest that it represents the late stage of the disease and that the atrophied mucosa is no longer able to respond to further microbial invasion." (PMID 40468054, 2025). "However, more long-term studies are required to investigate the specific molecular mechanisms between MMP-2 and MMP-9 and determine the clinical utility of specific protease inhibitors in tympanosclerosis and other pathologic processes." (PMID 40468054, 2025). "In conclusion, the relationship between MMP-2 and MMP-9 may play an important role in the pathogenesis of the development of tympanosclerosis against the background of chronic inflammation." (PMID 40468054, 2025). "According to the results of our study, it was thought that MMP-2 may play a role in the late and more sclerotic period of tympanosclerosis, and MMP-9 may play a role in the pre-tympanosclerosis period of COM." (PMID 40468054, 2025). "High rates of MMP-2 staining in hard plaques compared with soft plaques suggest that MMP-2 represents the late period when the disease is more severe, and MMP-9 is less stained in both soft and hard plaques, suggesting that MMP-9 is suppressed in the late stage of tympanosclerosis." (PMID 40468054, 2025). "In the literature, there are no studies investigating the presence of MMP-2 and MMP-9 together in sclerotic tissues and their effect on the disease in patients with tympanosclerosis." (PMID 40468054, 2025).
unstable angina pectoris (1 paper, 2021). "Peripheral sCD100 and MMP-2 level, as well as mCD100 level on T cells was assessed in patients with stable angina pectoris (SAP), unstable angina pectoris (UAP), and AMI." (PMID 33593275, 2021).
uremia (1 paper, 2017). A clinical syndrome associated with the retention of renal waste products or uremic toxins in the blood. "PMet newborn presented increase in uremia and CRP and significant rise of active MMP-2 and MMP-9 forms." (PMID 28133545, 2017).
urinary obstruction (1 paper, 2022). "An in vivo model of renal ischemia demonstrated increased MMP-2 protein levels in renal tissue and increased active isoform of MMP-2 protein in urine in response to oxidative stress or hypoxia, which is highly relevant in urinary obstruction." (PMID 35834547, 2022).
Uterine leiomyoma (1 paper, 2022). The presence of a leiomyoma of the uterus. "The expression of MMP2/9 has increased to damage the extracellular matrix, and uterine leiomyoma's invasiveness was enhanced." (PMID 35113040, 2022). "Moreover, the expression of MMP2/9 was decreased, and the invasiveness of uterine leiomyoma cells was weakened." (PMID 35113040, 2022). "In addition, the expression of MMP2/9 was decreased, and the metastasis and invasion of uterine leiomyoma were weakened." (PMID 35113040, 2022). "Furthermore, miR-29 inhibitors promoted the protein expression of MMP-2 and MMP-9 (P < 0.01), and EMT promoting proteins N-cadherin, snail, vimentin, and Transwell assay showed that miR-29 inhibitors promoted cell migration in uterine leiomyoma (P < 0.01)." (PMID 35113040, 2022).
uterine serous carcinoma (1 paper, 2010). "MMP-2, -7 and -9 were found to be expressed in uterine serous carcinoma as well as in endometrioid carcinoma of the uterus by immunohistochemistry." (PMID 20942921, 2010).
varicocele (1 paper, 2019). A condition characterized by the dilated tortuous veins of the spermatic cord with a marked left-sided predominance. "MMP-2 and MMP-9 have been found in the interstitium and seminiferous tubules, while the changes in MMPs in varicocele are controversial: decreased MMP-2 and MMP-9 levels have been reported in experimental varicocele, while a higher expression of MMP-9 has been reported in varicocele patients." (PMID 31110554, 2019).
ventricular fibrillation (1 paper, 2019). A disorder characterized by an electrocardiographic finding of a rapid grossly irregular ventricular rhythm with marked variability in QRS cycle length, morphology, and amplitude. "In a canine ventricular fibrillation (VF) model, the ratios of MMP-2/TIMP-2 were higher, and the Cx43 level was significantly decreased." (PMID 30805212, 2019).
verrucous carcinoma (1 paper, 2015). A well differentiated squamous cell carcinoma characterized by a papillary growth pattern, acanthosis, mild cytologic atypia, and pushing tumor margins. "In contrast, a study from China, found that MMP-2 expression was greater in the less aggressive verrucous carcinomas when compared with OSCC." (PMID 26155333, 2015).
villous adenocarcinoma (1 paper, 2014). An adenocarcinoma characterized by the presence of a villous architectural pattern. "The overexpression of the matrix extracellular genes ITGA-3 and ITGB-5 is associated with advanced stage tumors, and the genes MMP-2 and MMP-9 are overexpressed in mucinous and villous adenocarcinoma type tumors, respectively." (PMID 24737953, 2014). "The MMP-2 gene showed significant overexpression in mucinous type tumors, and MMP-9 was overexpressed in villous adenocarcinoma histologic type tumors." (PMID 24737953, 2014).
viral pneumonia (1 paper, 2025). Inflammation of the lung parenchyma that is caused by a viral infection. "Finally, threefold cross-validation was performed using a Random Forrest (RF) algorithm, with all combinations of IL-6, LIGHT, and MMP-2, to determine which combinations could most accurately predict whether a patient had viral or non-viral pneumonia." (PMID 41488910, 2025).
vitiligo (1 paper, 2025). Generalized well circumscribed patches of leukoderma that are generally distributed over symmetric body locations and is due to autoimmune destruction of melanocytes. "Previous studies in Drosophila and human skin disorders, such as vitiligo, have similarly implicated MMP2 in ECM destabilization and loss of epithelial adhesion." (PMID 40960906, 2025).
Wilson disease (1 paper, 2023). A very rare inherited multisystemic disease presenting non-specific neurological, hepatic, psychiatric or osseo-muscular manifestations due to excessive copper deposition in the body. "MMP2 serum levels are higher in patients with Wilson’s disease compared to healthy controls, supporting our findings of the association of cardiac Cu content with Mmp2 expression in BXDs." (PMID 36818345, 2023).
ZIKV infection (1 paper, 2020). "However, quantitative reverse transcription polymerase chain reaction (qRT-PCR) revealed that ZIKV infection did not affect MMP2 mRNA expression in whole blood." (PMID 32302362, 2020).
tumor (4,083 papers, 1996 to 2026). "Despite the advantages of ERMs in reducing systemic toxicity through tumor-associated enzyme targeting (e.g., MMP-2, HAase), their efficacy faces intrinsic challenges due to basal enzyme activity in healthy tissues." (PMID 40909221, 2025). "The results of this complex network model highlight the importance of exploring alternative approaches to target the enzymatic activity of tumour-associated MMP2 and MMP9." (PMID 40259907, 2025). "Higher levels of MMP2/7/10-encoded proteins (middle or high) were observed in tumor tissues, with MMP2/11/14 closely associated with different cancer stages (p<0.05)." (PMID 39773048, 2025). "Since NF-κB activation is closely associated with tumor invasion and metastasis, primarily through the regulation of matrix metalloproteinase-2 (MMP-2), we subsequently examined the MMP-2 signal in MDA-MB-468 cells treated with HMGB1." (PMID 40277915, 2025). "MMPs are involved in inflammation, and increased Mmp13 and Mmp2 expression is associated with increased tumor invasion and cancer progression." (PMID 40437307, 2025). "MMP-15 (MT2-MMP), encoded on chromosome 16, is a membrane-bound metalloproteinase implicated in extracellular matrix remodeling and MMP-2 activation, influencing tumor invasion." (PMID 41281748, 2025). "MMP-2 is implicated in tumor invasion and metastasis, particularly in esophageal cancer, and targeting it with siRNA has shown promise in reducing lung cancer growth." (PMID 41281748, 2025). "Matrix metalloproteinase 2 (MMP‐2) is one of the MMPs family associated with tumour growth, invasion, metastasis, and neoangiogenesis." (PMID 40118773, 2025). "We also analyzed the association between MMP-2 expression and tumor-infiltrating lymphocytes (TILs) to elucidate the immunological landscape of COAD." (PMID 40611940, 2025). "Conversely, under hypoxic conditions, CAPE significantly amplified the release of pro-tumorigenic factors, including the mediator facilitating tumor cell migration, invasion, and angiogenesis such as IL-8 and the invasion-associated metalloproteinase MMP-2." (PMID 41515435, 2025). "Existing research has implicated MMP2 as potentially upregulated in certain cancers, particularly within CAFs situated in the tumor’s periphery." (PMID 39950116, 2025). "Stromal cells, including CAFs and tumor-associated macrophages (TAMs), secrete MMP2 and MMP9, driving ECM degradation." (PMID 39940643, 2025). "For instance, targeting specific MMPs associated with distinct stages of metastasis, such as MMP-2 in tumor invasion or MMP-9 in angiogenesis, offers a more refined approach." (PMID 41409250, 2025). "Biochemical and structural analyses subsequently mapped CTX mechanisms of action, revealing direct interactions with tumor-associated membrane proteins, such as MMP-2 and NRP1." (PMID 41155199, 2025). "Upon reaching the tumor site, the degradative action of MMP‐2 causes the nanoparticles to shrink in size, further promoting drug release and penetration into tumor tissue." (PMID 41144769, 2025). "Tumour migration, invasion, and proliferation were significantly associated with E‐cadherin, vimentin, β‐catenin, MMP‐2, and MMP‐9." (PMID 40468625, 2025). "These ROS cause DNA damage and activate matrix metalloproteinases (MMP-2/9), facilitating pleural invasion by enabling tumor cells to breach the pleural barrier—especially in lower lobe NSCLC tumors." (PMID 41142602, 2025). "MMP2 has long been known to be involved in tumor invasion and has been prognostically linked to many cancer types." (PMID 40014866, 2025).